RNF103 (ring finger protein 103)
Description:
Acts as an E2-dependent E3 ubiquitin-protein ligase, probably involved in the ER-associated protein degradation pathway.
Synonyms: hKF-1; Zfp-103; ZFP103; KF1; KF-1
Tractability: Antibody: UniProt predicts a signal peptide or a membrane-spanning region. PROTAC: ubiquitination databases record sites on it.
Gene: Protein-coding gene on chromosome 2 (86,603,395 to 86,623,877, reverse strand). Ensembl gene ENSG00000239305.
Subcellular location: Endoplasmic reticulum membrane
Pathways (Reactome):
Metabolism of proteins: ER Quality Control Compartment (ERQC)
Gene Ontology:
Molecular function: protein binding; ubiquitin-protein transferase activity; ubiquitin protein ligase activity
Biological process: ERAD pathway; protein ubiquitination; central nervous system development; endoplasmic reticulum mannose trimming
Cellular component: endoplasmic reticulum; endoplasmic reticulum membrane; endoplasmic reticulum quality control compartment
Genetic constraint (gnomAD): Loss-of-function variants: 21 observed, 64.42 expected, observed/expected ratio (o/e) 0.33, 90% interval 0.23 to 0.47. The upper end of that interval is the gene's LOEUF score, 0.47, which puts it in group 2 of 6, group 1 being the genes least tolerant of losing a copy. Missense variants: 710 observed, 835.4 expected, observed/expected ratio (o/e) 0.85, 90% interval 0.8 to 0.9. Synonymous variants: 291 observed, 302.47 expected, observed/expected ratio (o/e) 0.96, 90% interval 0.87 to 1.06.
Homologues: Orthologues: chimpanzee RNF103 (99% identical), macaque RNF103 (99% identical), dog RNF103 (98% identical), pig RNF103 (97% identical), mouse Rnf103 (95% identical), rat Rnf103 (95% identical), rabbit RNF103 (93% identical), guinea pig RNF103 (88% identical), tropical clawed frog chmp3 (82% identical), zebrafish rnf103 (70% identical).
Diseases named in the same sentence as RNF103 in open-access papers:
RNF103 is named in the same sentence as 10 diseases in open-access papers, as found by Europe PMC text mining. Sharing a sentence is not in itself a finding about the gene and the disease. The quoted sentences say what the papers report.
Alzheimer disease (2 papers, 2011). A progressive, neurodegenerative disease characterized by loss of function and death of nerve cells in several areas of the brain leading to loss of cognitive function such as memory and language. "Kf-1/RNF103 was identified as a gene highly expressed in the cerebral cortex of Alzheimer disease patients." (PMID 24957874, 2011).
depression (2 papers, 2025). "The genes FAM120A, BTBD9, and RNF103 have not been previously linked to cancer; rather, they have been associated with schizophrenia, restless leg syndrome, and depression, respectively." (PMID 40608007, 2025).
childhood asthma (1 paper, 2020). "The novel loci included SNPs in or near the DENND1B (DENN domain containing 1B) gene, which has been implicated in childhood asthma; RNF103 (ring finger protein 103), a suspected antidepressant target and genes related to axon guidance (DCC netrin 1 receptor)." (PMID 31576797, 2020).
RNF103 also shares sentences with these, for which no sentence is quoted: Anxiety (1 paper); cancer (1); Cognitive impairment (1); glioma (1); infection (1); restless leg syndrome (1); schizophrenia (1).